CIROZ (ciliated left-right organizer protein containing ZP-N domains)
Description:
Plays a role in left-right patterning process.
Synonyms: C1orf127; FLJ37118; HTX14
Gene: Protein-coding gene on chromosome 1 (10,946,471 to 10,982,076, reverse strand). Ensembl gene ENSG00000175262.
Subcellular location: Secreted
Subcellular location (Human Protein Atlas): Cytosol; Nuclear speckles
Genetic constraint (gnomAD): Loss-of-function variants: 47 observed, 63.43 expected, observed/expected ratio (o/e) 0.74, 90% interval 0.58 to 0.94. The upper end of that interval is the gene's LOEUF score, 0.94, which puts it in group 4 of 6, group 1 being the genes least tolerant of losing a copy. Missense variants: 975 observed, 1,041.5 expected, observed/expected ratio (o/e) 0.94, 90% interval 0.89 to 0.99. Synonymous variants: 421 observed, 437.86 expected, observed/expected ratio (o/e) 0.96, 90% interval 0.89 to 1.04.
Homologues: Orthologues: chimpanzee C1H1orf127 (97% identical), macaque C1H1orf127 (86% identical), rabbit CIROZ (53% identical), mouse Gm572 (51% identical), rat C5h1orf127 (30% identical), zebrafish si:ch211-129o18.4 (17% identical).
Diseases named in the same sentence as CIROZ in open-access papers:
CIROZ is named in the same sentence as 1 disease in open-access papers, as found by Europe PMC text mining. Sharing a sentence is not in itself a finding about the gene and the disease.
CIROZ shares sentences with these, for which no sentence is quoted: autosomal recessive disease (1 paper).